EFNB2 (ephrin B2)
Description:
Cell surface transmembrane ligand for Eph receptors, a family of receptor tyrosine kinases which are crucial for migration, repulsion and adhesion during neuronal, vascular and epithelial development. Binds promiscuously Eph receptors residing on adjacent cells, leading to contact-dependent bidirectional signaling into neighboring cells. The signaling pathway downstream of the receptor is referred to as forward signaling while the signaling pathway downstream of the ephrin ligand is referred to as reverse signaling. Binds to receptor tyrosine kinase including EPHA4, EPHA3 and EPHB4. Together with EPHB4 plays a central role in heart morphogenesis and angiogenesis through regulation of cell adhesion and cell migration. EPHB4-mediated forward signaling controls cellular repulsion and segregation from EFNB2-expressing cells. May play a role in constraining the orientation of longitudinally projecting axons. (Microbial infection) Acts as a receptor for Hendra virus and Nipah virus.
Synonyms: HTK-L; EPLG5; HTKL; LERK5; MGC126226; MGC126227; MGC126228; ephrin-B2
Tractability: Small molecule: it has a high-quality binding pocket. Antibody: UniProt places it where antibodies can reach, with high confidence; its Gene Ontology location is reachable by antibodies, with high confidence; UniProt predicts a signal peptide or a membrane-spanning region. PROTAC: ubiquitination databases record sites on it; its protein half-life has been measured. Other modalities: a drug acting on it is in phase 2 or 3 trials.
Gene: Protein-coding gene on chromosome 13 (106,489,745 to 106,535,662, reverse strand). Ensembl gene ENSG00000125266.
Subcellular location: Cell membrane; Cell junction, adherens junction
Subcellular location (Human Protein Atlas): Nucleoplasm; Cytosol
Pathways (Reactome):
Developmental Biology: EPH-Ephrin signaling; EPH-ephrin mediated repulsion of cells; EPHB-mediated forward signaling; Ephrin signaling
Gene Ontology:
Molecular function: protein binding; receptor ligand activity; ephrin receptor binding; signaling receptor binding
Biological process: angiogenesis; cell adhesion; cell migration involved in sprouting angiogenesis; ephrin receptor signaling pathway; negative regulation of neuron projection development; positive regulation of cell population proliferation; positive regulation of leukocyte adhesion to arterial endothelial cell; regulation of chemotaxis; anatomical structure morphogenesis; axon guidance; blood vessel morphogenesis; positive regulation of cardiac muscle cell differentiation; adherens junction organization; anatomical structure formation involved in morphogenesis; cellular response to lipopolysaccharide; presynapse assembly; regulation of postsynaptic membrane neurotransmitter receptor levels; regulation of postsynaptic neurotransmitter receptor internalization
Cellular component: cytosol; focal adhesion; nucleoplasm; plasma membrane; glutamatergic synapse; presynaptic membrane; adherens junction; dendrite; membrane; postsynaptic density membrane; Schaffer collateral - CA1 synapse
Genetic constraint (gnomAD): Loss-of-function variants: 3 observed, 29.67 expected, observed/expected ratio (o/e) 0.1, 90% interval 0.045 to 0.26. The upper end of that interval is the gene's LOEUF score, 0.26, which puts it in group 1 of 6, group 1 being the genes least tolerant of losing a copy. Missense variants: 260 observed, 438.76 expected, observed/expected ratio (o/e) 0.59, 90% interval 0.54 to 0.66. Synonymous variants: 167 observed, 174.32 expected, observed/expected ratio (o/e) 0.96, 90% interval 0.84 to 1.09.
Gene-disease validity (ClinGen):
ClinGen rates the evidence that EFNB2 causes each of these diseases.
congenital heart disease (autosomal dominant): Limited. A heart disease that is present at birth.
Homologues: Orthologues: chimpanzee EFNB2 (100% identical), macaque EFNB2 (99% identical), pig EFNB2 (97% identical), rat Efnb2 (97% identical), mouse Efnb2 (97% identical), rabbit EFNB2 (87% identical), guinea pig EFNB2 (85% identical), tropical clawed frog efnb2 (82% identical), zebrafish efnb2a (65% identical), zebrafish efnb2b (56% identical), Drosophila melanogaster Ephrin (31% identical), Caenorhabditis elegans vab-2 (23% identical), and 3 more. Paralogues in human: EFNB1 (55% identical), EFNB3 (40% identical), EFNA3 (17% identical), EFNA5 (16% identical), EFNA1 (15% identical), EFNA2 (15% identical), EFNA4 (13% identical).
Diseases named in the same sentence as EFNB2 in open-access papers:
EFNB2 is named in the same sentence as 160 diseases in open-access papers, as found by Europe PMC text mining. Sharing a sentence is not in itself a finding about the gene and the disease. The quoted sentences say what the papers report.
breast carcinoma (28 papers, 2008 to 2025). "Apart from its role in physiological development and homeostasis, reverse signaling has also been described in tumor progression showing diverse effects, for example breast cancer-associated angiogenesis and increased glioma cell motility via ephrin-B2." (PMID 28698473, 2017). "EFNB2 overexpression is associated with poor outcome in thyroid cancer, glioblastoma, and cholangiocarcinoma, as well as pancreatic, bladder, ovarian, and endometrial carcinomas, whereas it is associated with a favorable prognosis in breast cancer." (PMID 41516312, 2025). "In contrast, a recent study in breast cancer cells reported that higher expression of EFNB2 may be associated with delayed metastasis and better prognosis by reducing cell proliferation, migration, and invasion." (PMID 35565468, 2022). "Besides, EphA4 receptor is overexpressed in the EMT/stem‐like breast cancer cells and Ephrin B2 is associated with progression and resistance to chemotherapy and radiation therapy in HNSCC." (PMID 31600013, 2020). "EFNB2 expression has also been associated with cellular proliferation, cell migration, angiogenesis and the progression of a wide range of human cancers, including malignant melanoma, small cell lung carcinoma, osteosarcoma, endometrial cancer, colon/colorectal carcinoma and breast cancer." (PMID 19259415, 2008). "EFNB2 plays a tumor-promoting role in pancreatic ductal adenocarcinoma, breast cancer, and glioblastoma." (PMID 36376513, 2023). "It has been reported that Ephrin-B2 inhibits cell proliferation and motility in vitro and predicts longer metastasis-free survival in breast cancer." (PMID 37958393, 2023). "BB was also reported to suppress migration by targeting ephrin-B2 then decreased MMP-2/9 protein expression in breast cancer ZR-75-30 cells." (PMID 34771481, 2021). "In MCF-7 breast cancer cells, on the other hand, EphB4 displayed pro-oncogenic effects, via ephrin-B2-mediated activation of the extracellular signal-regulated kinase (ERK) pathway, which has been linked to the promotion of protein phosphatase." (PMID 33430066, 2021). "When stimulated by its preferred ligand, ephrin-B2, EphB4 behaved as a tumour suppressor in a mouse xenograft model of breast cancer." (PMID 33430066, 2021). "Existing evidence also showed that EphB4 was expressed on the surface of breast cancer cells that promote angiogenesis in tumor xenografts by activating Ephrin-B2 reverse signaling in the vasculature, thus increasing tumor growth." (PMID 32733636, 2020). "EFNB2 repression induced tumor migration and invasion in human gliomas and breast cancer, which was similar to our results." (PMID 33585562, 2020). "The TNYL-RAW peptide has been shown to inhibit EphB4 tyrosine phosphorylation (activation) induced by ephrin-B2 in cultured MCF7 breast cancer cells and human umbilical vein endothelial cells (HUVECs)." (PMID 22194865, 2011). "Ephrin-B2 expression was shown to have negative effects on proliferation and motility and to be associated with longer patient survival in breast cancer." (PMID 34360867, 2021). "Accordingly, high levels of EphB4 expression in breast cancer cell lines was found to be often accompanied by low expression of its ligand, ephrin-B2, and this allows for signalling via ligand-independent pathways and evasion of EphB4’s tumour-suppressing effects." (PMID 33430066, 2021). "The same finding was observed in the MCF10A-derived model of breast cancer progression, whereby both the invasive (CA1ACL1 and CA1DCL1) and the DCIS.com cell variants co-expressed higher levels of EphB2, EFNB1, and EFNB2 than the benign parental MCF10A cell line." (PMID 34360867, 2021). "Although we found that EPHB2 was the most promising candidate in our breast cancer cohorts, EPHB2 together with EPHB6, EPHA2, EPHA4 and the ligands EFNB1 and EFNB2 were important to define prognostic relevant clusters." (PMID 26870995, 2016).
breast carcinoma (continued). "In prostate cancer 22Rv1 and breast cancer MCF7-10A cells, EPHB4 suppressed cancer cell growth via EPHB4/EFB2 signalling pathway in the presence of EFNB2; however, EPHB4 promoted cancer cell growth in the absence of EFNB2." (PMID 28035996, 2016). "Similarly, a previous study demonstrated that an EPHRIN B2-induced EPHB4 signaling cascade, mediated by the Abl-Crkl pathway, resulted in apoptosis in mammary carcinoma." (PMID 33816783, 2021). "We also suggest that EFNB1 and EFNB2 could be additional interesting candidates and revealed the clinical value of EPHB2 as a potential prognostic marker in breast cancer." (PMID 26870995, 2016). "Especially EPHA2, EPHA4, EFNB1, EFNB2, EPHB2, and EPHB6 and their co-expression in breast cancer." (PMID 26870995, 2016). "For instance, TNYL-RAW has been recently used to demonstrate that ephrin-B2 has effects in endothelial cells that are independent of interaction with EphB4 and that EphB4 has effects in breast cancer cells that are independent of interaction with ephrin-B2." (PMID 22194865, 2011).
glioma (20 papers, 2012 to 2025). A benign or malignant brain and spinal cord tumor that arises from glial cells (astrocytes, oligodendrocytes, ependymal cells). "Stimulation of glioma cells with their specific ligand, ephrin-B2, induces EphB4 phosphorylation, which suppresses migration, invasion, and Akt signaling." (PMID 41200151, 2025). "Mechanistically, EphB1 lacks detectable tyrosine phosphorylation in glioma cells and, when overexpressed, inhibits ephrin-B2-induced migration and invasion both in vitro and in vivo." (PMID 41200151, 2025). "Ephrin-B2 overexpression characterized glioma tissue specimens, while its phosphorylation was shown to promote tumor invasion, as well as angiogenesis via vascular endothelial growth factor receptor 2 (VEGFR2) regulation." (PMID 38612645, 2024). "We further strengthened this argument by correlating the expression of the two VEGFR2 subunit genes FLT1 and KDR with the expression of EFNB2 in Glioma." (PMID 35629359, 2022). "Recently, it was shown that EphB4 receptor activation by ephrin-B2 suppresses glioma migration and invasion via the suppression of Akt phosphorylation." (PMID 35448036, 2022). "Increased EFNB2 expression in glioma was shown to result in a significant reduction in patient survival." (PMID 35629359, 2022). "Histological analysis of glioma tissue shows increased, global expression of EFNB2 and some EPHB4 expression in tumor cells." (PMID 35629359, 2022). "Since EphA2, EphA3 and ephrin-B2 were described to regulate tumor-propagating cell self-renewal, luciferase-transfected glioma stem cells (TPC8 cell line) were injected into mouse brains." (PMID 29849945, 2018). "It is unclear which molecules are implicated in the phenotypic changes of glioma cells downstream of ephrin-B2 and how EphB1-ephrin-B2 interactions cooperatively regulate the cellular behavior of glioma cells." (PMID 28194092, 2017). "Upregulation of ephrin-B2/EphB4 has been observed in many tumors, including ovary, colon, breast, and glioma, with a strong correlation with poor prognosis." (PMID 22292016, 2012). "Furthermore, high ephrin-B2 expression serves as a strong predictor of shorter survival in glioma patients, underscoring its potential as a prognostic biomarker." (PMID 41179304, 2025). "Analogous findings have been reported for ephrins, with increased expression of ephrin-A3 and ephrin-A4 in ependymoma cell lines, of ephrin-B1 in medulloblastoma cell lines and rhabdomyosarcoma tumor cells, and of ephrin-B2 in gliomas and rhabdomyosarcoma tumor cells." (PMID 38612645, 2024). "EphrinB2 reverse signaling triggers substantial morphological changes and increased motility, aligning with previous findings demonstrating that ephrin-B2 reverse signaling increases the motility of glioma cells." (PMID 38811954, 2024). "EphB4/ephrin-B2 is highly expressed in many malignant tumor cells, including glioma cells." (PMID 35448036, 2022). "However, EphB1 partially abrogates the migration and invasion induced by ephrin-B2 reverse signaling in glioma cells." (PMID 28194092, 2017). "Towards this direction, EPHB4/ephrin-B2 signaling is explored as an antiangiogenic target, with anti-EPHB4 monoclonal antibodies successfully blocking EPHB4 signaling, while inhibition of EPHA2 and EPHB1-3 forward signaling in gliomas is associated with a dose-dependent reduction in cell invasion." (PMID 38612645, 2024). "Specifically, the observation that a high expression of EPHA2 in neuroblastoma, EPHB1 in glioma, EPHB6, ephrin-B2, and ephrin-B3 in neuroblastoma correlates with a better prognosis is in line with a tumor-suppressive role of these EPHs." (PMID 38612645, 2024). "On the other hand, high expression levels of EPHA2 in neuroblastoma, of EPHB1 in glioma, and of EPHB6, ephrin-B2 and ephrin-B3 in neuroblastoma confer a better prognosis." (PMID 38612645, 2024).
glioma (continued). "In addition, knock down of the gene encoding for ephrins (EFNB2) in GSC derived from patients’ samples or treating tumours generated from these GSC with anti-ephrin-B2 antibodies, showed a significant reduction in the initiation and progression of glioma tumourigenesis." (PMID 29113105, 2017). "The RTK ligands including EFNB2, SEMA3D, PDGFA, SEMA3A and FGF14 were amplified in ~5% of the RMPAhigh gliomas." (PMID 27385209, 2016).
colorectal cancer (14 papers, 2004 to 2023). A primary or metastatic malignant neoplasm that affects the colon or rectum. "The variant rs7983579, which is in LD with rs9520090 (r2 = 0.8) in EFNB2, was significantly associated with the overall survival of colorectal cancer patients (HRT > G: 1.76, 95% CI: 1.14–2.73, p-value: 0.01)." (PMID 32751332, 2020). "No other gene, which may be relevant for cancer progression is located in the vicinity of this region, thus it seems plausible, that the identified associations with survival of colorectal cancer patients are linked to EFNB2." (PMID 32751332, 2020). "Furthermore, we had access to two validation sets and validated the association of the EFNB2 tagging SNP rs9520090 (or its linked variant rs7983579) with the overall survival of colorectal cancer." (PMID 32751332, 2020). "EFNB2 is expressed at abnormally high levels in some neoplasms, such as squamous cell carcinoma of the head and neck and colorectal cancer." (PMID 33828969, 2021). "Eleven tagging SNPs in four genes (EFNB2, MMP2, JAG1 and KDR) were significantly associated with overall survival of colorectal cancer patients." (PMID 32751332, 2020). "In this study, we observed significant associations between five variants in ephrin B2 (EFNB2) and OS of colorectal cancer patients." (PMID 32751332, 2020). "Upregulation of ephrin-B2 was also found in colorectal cancer cell lines, COLO205 and HT108 both in cell culture and as a tumor xenograft in mice." (PMID 22292016, 2012). "Like EFNB2, ANGPTL4 has also been associated with the development of a range of cancers, including colorectal cancer, renal cell carcinoma, bladder tumours and gastric cancer." (PMID 19259415, 2008). "Our group has shown that EphB and the ephrin-B subfamilies are coexpressed in human colorectal cancer, and ephrin-B2 is expressed at higher levels in human colorectal cancer than in adjacent normal mucosa." (PMID 15083195, 2004). "Herein, we found that EFNB2 expression was upregulated in liver metastases (LM) of colorectal cancer (CRC), but not in pulmonary metastases (PM) or primary CRC tumors." (PMID 36376513, 2023).
glioblastoma (13 papers, 2013 to 2026). The most malignant astrocytic tumor (WHO grade IV). "Downregulation of S1PR1 expression has been shown to increase proliferative activity resulting in enhanced malignancy and poor survival of glioblastomas while high-level expression of transcripts encoding ephrin-B2 has been reported as predictive of favourable disease outcome of neuroblastoma." (PMID 23526956, 2013). "EFNB2 emerged as the hub gene and was enriched in glioblastoma, and EFNB2-positive malignant cells displayed prominent communication with neurons, including EFNB2-EPHB1 signaling." (PMID 42196284, 2026). "EFNB2 was also reported to drive perivascular invasion and proliferation of glioblastoma stem-like cells." (PMID 28035996, 2016). "Using antibodies to block ephrin-B2 in tumors greatly reduced tumor size and extended survival in mice with glioblastoma tumors." (PMID 27350048, 2016). "On the other hand, TNC generates ephrin-B2 and a pro-angiogenic secretome in glioblastoma cells." (PMID 39090080, 2024). "Notably, high expression level of the synaptogenesis marker EFNB2 correlates with lower overall survival of GB patients (TCGA data), evidencing its clinical relevance in glioblastoma." (PMID 37833281, 2023). "EFNB2 has been shown to mediate perivascular invasion of glioblastoma stem-like cells." (PMID 32211330, 2020). "The experiments suggest the blocking ephrin-B2 might be a therapy that both stops the glioblastoma cells from spreading and prevents the tumor cells from multiplying." (PMID 27350048, 2016).
head and neck squamous cell carcinoma (13 papers, 2010 to 2025). A squamous cell carcinoma that arises from any of the following anatomic sites: lip and oral cavity, nasal cavity, paranasal sinuses, pharynx, larynx, and salivary glands. "Moreover, the overexpression of EphB4 and EFNB2 is associated with poor prognosis in head and neck squamous cell carcinoma patients and may serve as valuable prognostic markers." (PMID 40181975, 2025). "We used orthotopic models of head and neck squamous cell carcinoma to determine the role of EphB4-ephrin-B2 interaction in tumor immune microenvironment." (PMID 30400822, 2018). "Several groups showed that the level of ephrin-B2 was significantly increased in head and neck squamous cell carcinoma (HNSCC) and that there was a correlation between elevated ephrin-B2 protein level and poor prognosis." (PMID 29190834, 2017).